KRAS (KRas proto-oncogene, GTPase)
Diseases named in the same sentence as KRAS in open-access papers (continued):
Sharing a sentence is not in itself a finding about the gene and the disease.
tumor (continued). "An ongoing trial is evaluating the combination in patients with prior PARPi exposure or KRAS-mutated tumours (NCT05327010)." (PMID 37430137, 2023). "In the patients with CRC, PR-Score was associated with the clinicopathologic features such as tumor stage, lymphatic invasion, and KRAS mutation." (PMID 36741232, 2023). "Tumor cells carrying KRAS mutations are endowed with cellular proliferation and survival, and they accumulate in tumor patients." (PMID 37828002, 2023). "But KRAS was considered undruggable for quite a long period, and tumours with KRAS mutation tended to have a worse outcome." (PMID 37509345, 2023). "Briefly, subtype 1 called ‘piano’ tumours had the least number of mutations growing slowly over the years, with the most frequently mutated gene being KRAS." (PMID 37686122, 2023). "PAAD-C1 had a lower mutation rate, including lower fraction of tumors with mutated KRAS, but this is likely because of the high stroma fraction and lower overall tumor cell percentage in these cases." (PMID 37414817, 2023). "Mutations of KRAS are expressed in multiple tumour types, most notably in NSCLC at a rate of approximately 25–30%." (PMID 38067288, 2023). "With LOHHLA analysis demonstrating intact HLA-A*11:01 in this organoid, this again suggested decreased MHC-peptide complex on the tumor surface due to insufficient expression of the KRAS G12D allele or a defect in its processing and loading onto MHC." (PMID 37368077, 2023). "The results showed that ROS1 gene mutations, tumor stage, and the endocrine system diseases history were independent adverse prognostic factors, while KRAS gene mutations were independent prognostic protective factors." (PMID 37468609, 2023). "The intrinsic and extrinsic mechanisms by which KRAS mutations and tumour PD-L1 expression remodel the immune landscape of the TME have become a focus of research in recent years." (PMID 36864508, 2023). "Among those with NSCLC harboring KRAS G12C mutations, a reduction in tumor volume was reported in 43%." (PMID 37894382, 2023). "Mutations in some of its components, such as KRAS, produce an oncological activation of this pathway that significantly contributes to cell transformation and is unquestionably involved in tumor progression." (PMID 37996408, 2023). "Curiously, both KEAP1 and STK11 mutations are associated with worse prognosis in tumours harbouring KRAS G12C mutations compared to G12V or G12D." (PMID 36864508, 2023). "On the KRAS gene, the effector domain is found in exons 1 and 2, which are also mutational hotspots, and it has been shown that mutations in the KRAS effector domain can alter tumor progression." (PMID 36830680, 2023). "In vitro and in vivo studies have demonstrated that co-occurring mutations of STK11 and KEAP1 in KRAS-mutant NSCLC promote tumor growth and confer enhanced resistance to radiotherapy." (PMID 37675220, 2023). "On in vitro KRAS mutated spheroid simulation, the model output matched the experimental data, both in terms of tumor radius evolution, and maximal depth for cell viability observed in these conditions." (PMID 37524705, 2023). "Circulating tumour DNA (ctDNA) of patients with G12 and G13 KRAS mutations was detected and quantified." (PMID 37316578, 2023).
tumor (continued). "KRAS oncogenic mutations are not only responsible for malignant cell transformation and tumor development but also related to poor prognosis, low survival rate, and resistance to chemotherapy." (PMID 37376135, 2023). "GSVA enrichment analysis showed that m5C-associated lncRNAs were significantly associated with pathways related to tumor progression, such as KRAS signaling pathway, PI3K-AKT-mTOR signaling pathway, MYC targets and TGF-BETA signaling pathway, and so on." (PMID 37670275, 2023). "The high APMHO subgroup showed enrichment in several tumor-associated pathways including hypoxia, unfolded protein response, mTORC1 and Glycolysis signaling, while the KRAS signaling pathway was relatively downregulated in this subgroup." (PMID 37897503, 2023). "In P4 and P5, tumor KRAS profiling was performed 1 month before ctDNA testing; therefore, the low-frequency KRAS mutation in ctDNA suggests the detection of minimal residual disease levels." (PMID 37511664, 2023). "A study of 419 CRC patients with unresectable liver metastases showed that the KRAS A146 mutations had a high tumor burden (TMB) and a worse OS compared with the G12 subtypes (median OS 10.7 months vs. 26.4 months; p = 0.003)." (PMID 36675641, 2023). "Regaining KRAS gene function due to mutations is common in many tumor types, particularly those of the gastrointestinal tract." (PMID 37509254, 2023). "Growing evidence supports the proposition that mutated KRAS play a carcinogenic role by increasing tumor blood vessels, tumor invasiveness, matrix remodeling and immunosuppression." (PMID 37670322, 2023). "Most of the cases that harboured KRAS mutations either in CTCs or in tumour tissues had higher KRAS expression." (PMID 37761948, 2023). "We recently reported that GNAS mutations inhibit tumor cell invasion by suppressing the KRAS pathway in PDAC." (PMID 37470859, 2023). "Group 1 tumor spheroids are highly enriched for programs associated the epithelial–mesenchymal transition, KRAS signaling, and Myc activity and express high levels of the metastasis markers, such as Vimentin, TWIST1, and ZEB2." (PMID 37728504, 2023). "THZ1 (5 and 10 mg/kg, twice per day) significantly hindered the growth of xenograft PDAC tumours in mice derived from CAPAN2 cells with KRAS‐G12V mutation in a dose‐dependent manner." (PMID 38037549, 2023). "Multiple independent studies have demonstrated that tumor cells with endogenous KRAS mutations have enhanced macropinocytosis, which is oncogenic KRAS-dependent." (PMID 35154489, 2022). "In this tumor type, close to 90% of all KRAS mutations affect codon 12, although codons 13 and 61 are also mutated at lower frequencies." (PMID 34951114, 2022). "Simultaneously, effects of KRAS mutations on tumour microenvironment were also discovered, partly owing to the universal use of immune checkpoint inhibitors." (PMID 36284306, 2022). "From 79,004 tumor samples analyzed, 13,758 KRAS-mutated tumors were identified from various cancer types." (PMID 35319967, 2022). "Only for patient C32, the KRAS mutation with a tumor AF of 23.82% was detected in the cfDNA sample at 1.48% AF." (PMID 35454937, 2022). "Most studies focusing on a single or few time points frequently report either a low number of resectable PDAC patients expressing KRAS mutations in plasma or substantially less than the number of positive tumor samples." (PMID 35448266, 2022).
tumor (continued). "In NSCLC, KRAS G12D mutation has been associated with a lower tumour-mutation burden, decreased PDL1 expression, and reduced CD8 + T cell infiltration in the TME." (PMID 36284306, 2022). "These KRAS mutants also discovered a positive correlation between tumor mutational burden (TMB) and PD-L1 expression status." (PMID 36136862, 2022). "The therapeutic potential for SBT-100 in vivo has been demonstrated here as monotherapy, we have confirmed the efficacy in the form of tumor regression in athymic nude mouse xenograft with TNBC tumors with KRAS(G13D) mutation (at least 50–100 mm3)." (PMID 35886918, 2022). "KRAS mutations in tumor cells increases the pool of cytokines secreted (GM-CSF, G-CSF, SHH), and, therefore, are exposed to CAFs in the TME." (PMID 36612058, 2022). "Co-occurring genomic alterations in KRAS-mutated tumors have an effect on the tumor biology and response to systemic therapies." (PMID 35267628, 2022). "The NGS GeneRead analysis of tumor tissue cells showed the consistent mutations of KRAS and ERBB2 as carried by urinary exosomes from the same BC patient." (PMID 35787656, 2022). "The colony formation, migration, invasion, adhesion, tumor perimeter, and mesenchymal phenotype were increased in the H292 KRAS mutated cells." (PMID 35887120, 2022). "Using a combined morphological and molecular approach we characterized the histological aspects of these tumors, including the tumor microenvironment landscape and the main molecular alterations associated with the KRAS G12C mutation." (PMID 35205778, 2022). "A KRAS mutation was identified in one of the two patients in whom a KRAS mutation was identified in tumor tissue." (PMID 35050442, 2022). "In parallel, ctDNA and fresh CTC DNA sampled at the time of inclusion, as well as DNA derived from Patient 13′s in ovo tumor 1, contained a Kirsten Rat Sarcoma Viral Oncogene Homolog (KRAS) p.Gly12Val somatic mutation." (PMID 36077622, 2022). "This work clarifies the prognosis significance of KRAS mutation-positivity in margins of resected tumours, using ultra-sensitive detection of KRAS mutations." (PMID 35194118, 2022). "KRAS activating mutations have been identified in 8–54% of patients with iCCA, and generally higher incidence of KRAS mutations are associated with increased tumor stage and poor prognosis." (PMID 36046845, 2022). "KRAS mutations were associated with tumour differentiation (P = 0.001), TNM stage (P = 0.013), and T stage (P < 0.001)." (PMID 36582783, 2022). "Its upstream activators, the rat sarcoma virus (RAS) family proteins, are among the most frequently mutated oncogenes in human neoplasms—particularly KRAS, which is involved in about 30% of human cancers." (PMID 36358725, 2022). "This meta-analysis included a large number of patients (n = 7475) with data on primary tumor side and KRAS mutational status." (PMID 35159066, 2022). "We analysed tumour tissue and performed DNA analysis for mutations in KRAS, BRAF and analyses for MSS/MSI in all patients except 8 of 257 (3.1%) where tumour tissue was not obtained." (PMID 34887523, 2022). "The phase I/II CodeBreaK100 trial explored sotorasib monotherapy in tumours harbouring a KRAS G12C mutation." (PMID 36284306, 2022).
tumor (continued). "These tumor-associated macrophages (TAMs) provide cancer cells with TGFβ that promotes KRAS mutation-independent PDAC cell growth after KRAS mutation-targeted inhibition." (PMID 35922812, 2022). "The blue line represents the KRAS-mutated tumours (mutKRAS) tumours and the green dotted line represents the BRAF-mutated microsatellite stable (MSS) (mutBRAF/MSS) tumours." (PMID 34887523, 2022). "The initial APC and KRAS mutations drive effective proliferation and growth, while inactivation mutations in Smad4 prevent differentiation during tumor progression." (PMID 35273961, 2022). "The findings that cytokine expression is influenced by KRAS signaling and mutations in KRAS are tightly linked to tumor‐promoting inflammation suggest a molecular link between inflammation and tumorigenesis and a viable therapeutic option for KRAS targeting." (PMID 35791509, 2022). "Among 151 patients, 65.4% who were positive for carriage of the KRAS mutation in their CRC tumor were from an urban area." (PMID 35057499, 2022). "A six-point prognostic model: node-positive primary (1 point), CEA >200 ng/mL or CA19-9 >200 U/mL (1 point), KRAS/NRAS/BRAF-mutated tumor (1 point) extrahepatic disease (1 point), mTBS between 5 and 11 (1 point) and mTBS more than 12 (2 points)." (PMID 35804994, 2022). "Among the earliest genetic events in adenoma formation, mutations in the APC tumour suppressor and the KRAS proto-oncogene cause hyperactivation of the pro-proliferative Wnt and MAPK signalling pathways, respectively." (PMID 36477656, 2022). "In contrast, although either AMG-510 or anti- PD-1 monotherapy caused tumor complete regression in only one out of ten mice, for each therapy; combined treatment achieved a complete and prolonged response in 9/10 CT-26 KRAS G12C mice." (PMID 35251972, 2022). "In the present study, two genetic mutations (KRAS + PIK3CA) were sufficient to induce LGSOC tumor growth and progression in nude mice." (PMID 35326657, 2022). "Consistent with previous data, all four tumors whose tumor tissues were available for targeted sequencing harbored pathogenic KRAS mutations." (PMID 35204416, 2022). "Ongoing investigation into rational combinations, both in the salvage setting and in the first-line setting, will increase the impact of both sotorasib and adagrasib in NSCLC and potentially in other tumours with KRAS G12C mutations." (PMID 36284306, 2022). "KRAS G12C is an activator mutation of the KRAS oncogene leading to increased levels of mutated KRAS oncoprotein and enhanced tumor viability." (PMID 35205778, 2022). "In the analysis, we determined and compared the VAFs of the KRAS mutations in tumor samples obtained by bulk, coring, and LMD techniques." (PMID 36266629, 2022). "In conclusion, our results unravel the developmental, tissular, cell-specific and subcellular expression profile of KRAS protein, and provide insight into the mechanisms conferring sensitivity to KRAS mutations during tumor initiation." (PMID 36238685, 2022). "“cell-free DNA” (cfDNA) is thought to be secreted through apoptosis and necrosis, and the kirsten rat sarcoma viral oncogene (KRAS) mutations detected in cfDNA were found of tumor origin, giving rise to the term ‘ctDNA’." (PMID 36713554, 2022). "PAT2 and PAT5 presented a double mutation in KRAS (p.G12V, p.G13D) in the primary tumor and only a single mutation (p.G13D) in the metastasis." (PMID 35936004, 2022). "Third, analyzing only the BRAF and KRAS hotspot variants limits the benefits of this method to patients carrying one of these variants in tumor tissue." (PMID 35159118, 2022).
tumor (continued). "As an example, in this panel, the KRAS G12C mutation was identified in the highly treatment-resistant PDX tumor Lu7198 and therefore this model was excluded from further experiments at this stage." (PMID 35039644, 2022). "In the FLAURA study, mutations of KRAS, like G12D and A146T, were described in the cfDNA of 3% of cases; in the study conducted by Schoenfeld on tumor tissue, KRAS mutation G12A was recorded in one case (4%)." (PMID 35267450, 2022). "More importantly, in this study although KRAS mutations were detected in two clinical cases, evident tumor inhibition was still observed after cetuximab treatment in both PDX models and patients." (PMID 36465411, 2022). "Tumors with KRAS codon 12 mutations tented to have high tumor budding with a difference close to significance, as compared with tumors harboring other KRAS codon mutations (P=0.05)." (PMID 35096426, 2022). "The pro-tumor inflammation caused by KRAS is associated with immune regulation, which leads to immune escape in the TME." (PMID 36330448, 2022). "KRAS mutation was significantly more common in MT-brain than described for extracranial tumor manifestations." (PMID 35912232, 2022). "For example, in some patients, a secondary G12V mutation was detected on the trans allele of KRAS of treatment-resistant tumor cells, which confers resistance to covalent G12C inhibitors." (PMID 36099883, 2022). "It has also been shown in Slc7a11 deficient mice that oncogenic KRAS-driven pancreatic adenocarcinoma (PDAC) tumor growth is significantly impaired." (PMID 35280777, 2022). "In the TRACERx study, multi-region whole-exome sequencing on 100 early-stage NSCLC tumours revealed 7 KRAS G12C-positive tumours, with one tumour harbouring co-occurring KRAS G12C and G12V mutations." (PMID 35177674, 2022). "Increasing studies have identified that KRAS is one of the most frequently mutated genes that impacts a multidomain group of intracellular signaling pathways that are involved in tumor cell growth, survival, and metastasis." (PMID 35563733, 2022). "Identifying an oncogenic mutation arising in the KRAS gene from the cell-of-origin prior to becoming a tumor is challenging in humans." (PMID 36069770, 2022). "KRAS G12C mutations were identified in 2985 of 80,911 patients (3.7%) across > 40 tumor types, as detected by circulating tumor DNA." (PMID 36139444, 2022). "Limited evidence exists, other than KRAS associations with tumor-suppressor genes or oncogenic drivers." (PMID 36661676, 2022). "Recent studies have shown a higher risk of tumor recurrence after surgical resection in early-stage cancers with KRAS G12C mutations in comparison to other KRAS-mutated tumors and non-KRAS-mutated tumors." (PMID 35406400, 2022). "Age, TNM stage, T stage, N stage, tumour differentiation, resection margin, presence of KRAS mutation, and KRAS wild-type status were associated with DFS after resection (P < 0.05)." (PMID 36582783, 2022). "KRAS mutations are more often associated with heavy smoking, higher tumor mutation burden (TMB), and PD-L1 expression mediated by ERK activation and a high level of tumor-infiltrating lymphocytes (TILs)." (PMID 35887766, 2022). "KRAS double mutations are described in the literature and, although rare events, they can represent an interesting clinical model to study tumor genetic evolution." (PMID 35936004, 2022).